CLEC16A (C-type lectin domain containing 16A)
Description:
Regulator of mitophagy through the upstream regulation of the RNF41/NRDP1-PRKN pathway. Mitophagy is a selective form of autophagy necessary for mitochondrial quality control. The RNF41/NRDP1-PRKN pathway regulates autophagosome-lysosome fusion during late mitophagy. May protect RNF41/NRDP1 from proteasomal degradation, RNF41/NRDP1 which regulates proteasomal degradation of PRKN. Plays a key role in beta cells functions by regulating mitophagy/autophagy and mitochondrial health.
Synonyms: KIAA0350; Gop-1
Tractability: Antibody: UniProt places it where antibodies can reach, with medium confidence. PROTAC: ubiquitination databases record sites on it; its protein half-life has been measured.
Gene: Protein-coding gene on chromosome 16 (10,944,539 to 11,182,186, forward strand). Ensembl gene ENSG00000038532.
Subcellular location: Endosome membrane; Lysosome membrane
Subcellular location (Human Protein Atlas): Nucleoplasm; Vesicles
Gene Ontology:
Biological process: cellular response to starvation; mitophagy; negative regulation of autophagosome maturation; positive regulation of TORC1 signaling; endosomal transport; regulation of autophagosome maturation; vacuolar transport
Cellular component: cytosol; Golgi apparatus; vesicle; late endosome; endosome membrane; lysosomal membrane
Genetic constraint (gnomAD): Loss-of-function variants: 45 observed, 90.35 expected, observed/expected ratio (o/e) 0.5, 90% interval 0.39 to 0.64. The synonymous counts are far from expectation, so gnomAD's model fits this gene poorly and the ratio says little. Missense variants: 1,252 observed, 1,323.5 expected, observed/expected ratio (o/e) 0.95, 90% interval 0.9 to 0.99. Synonymous variants: 638 observed, 540.93 expected, observed/expected ratio (o/e) 1.18, 90% interval 1.1 to 1.26.
Homologues: Orthologues: chimpanzee CLEC16A (99% identical), macaque CLEC16A (99% identical), guinea pig CLEC16A (94% identical), dog CLEC16A (93% identical), pig CLEC16A (93% identical), rabbit CLEC16A (93% identical), rat Clec16a (91% identical), mouse Clec16a (90% identical), tropical clawed frog clec16a (74% identical), zebrafish clec16a (62% identical), Drosophila melanogaster ema (46% identical), Caenorhabditis elegans gop-1 (30% identical).
Diseases named in the same sentence as CLEC16A in open-access papers:
CLEC16A is named in the same sentence as 38 diseases in open-access papers, as found by Europe PMC text mining. Sharing a sentence is not in itself a finding about the gene and the disease. The quoted sentences say what the papers report.
autoimmune disease (23 papers, 2013 to 2025). A disorder resulting from loss of function or tissue destruction of an organ or multiple organs, arising from humoral or cellular immune responses of the individual to their own tissue constituents. "The C-type lectin domain family 16, member A (CLEC16A) gene within the 16p13 region has consistently been shown to be associated with increased risk of developing both MS and other autoimmune disorders." (PMID 39940946, 2025). "These include Il-7 and its receptor Il7R, CD226, CAPSL, and CLEC16A, which appear to be attractive candidates for further studies to explore the pathogenic mechanisms and potential therapeutic options for autoimmune diseases." (PMID 38612837, 2024). "The CLEC16A gene has been described in broad association with autoimmune diseases, among them autoimmune thyroiditis and AAI." (PMID 39423205, 2024). "CLEC16A is emerging as an important genetic risk factor for several autoimmune disorders and for Parkinson disease (PD), opening new avenues for translational research and therapeutic development." (PMID 37175930, 2023). "CLEC16A is implicated in multiple autoimmune diseases and in the pathogenesis of Parkinson’s disease (PD)." (PMID 37175930, 2023). "CLEC16A also is genetically linked with many distinct autoimmune disorders, including but not limited to type-1 diabetes, multiple sclerosis, systemic sclerosis, systemic lupus erythematosus, and rheumatoid arthritis." (PMID 33927318, 2021). "The complexity of each condition, and the presence of different types of neuropathies across different autoimmune diseases, complicates the elucidation of how CLEC16A is related to sensory neuron loss." (PMID 33927318, 2021). "In summary, the autoimmune disorder susceptibility gene CLEC16A restrains NK cell function in the YTS NK cell line and Clec16a knockout mice." (PMID 30774629, 2019). "As a consequence, CLEC16A has become an attractive candidate for functional studies to explore the pathogenic mechanisms involved and potential therapeutic focus for autoimmune disorders." (PMID 30774629, 2019). "Given the association of CLEC16A to several autoimmune disorders we sought to understand the role of CLEC16A in immune cells." (PMID 30226884, 2018). "We report here that CLEC16A, which has been linked by GWAS studies to multiple sclerosis and other autoimmune diseases, has an important role in the survival of cerebellar Purkinje neurons in two mutant mouse models." (PMID 26987296, 2016). "Together with its selective expression in immune cells and due to its association with a wide variety of autoimmune diseases, the CLEC16A gene and the encoded molecule is indeed of interest for further functional studies." (PMID 23439554, 2013). "The broad association with autoimmune disorders suggests that CLEC16A may functionally link to autoimmunity by certain common pathogenic pathways." (PMID 35432448, 2022). "The shared association of CLEC16A in these diverse inflammatory and autoimmune diseases suggests that CLEC16A could be a critical regulator of autoimmune responses." (PMID 33795715, 2021). "As a consequence, CLEC16A has become an attractive candidate for functional studies to explore the pathogenic mechanisms and potential therapeutic options through CLEC16A intervention in autoimmune diseases." (PMID 33795715, 2021). "The study of Kim and colleagues suggests that CLEC16A might confer susceptibility to autoimmune disorders through its role in endosomal regulation of immune receptor signaling pathways, leading to aberrant immune responses of autoreactive T-cells." (PMID 23439554, 2013). "Thus, CLEC16A is becoming an attractive candidate for functional studies to explore the pathogenic mechanisms and therapeutic options through interventions at the protein level of CLEC16A in autoimmune diseases." (PMID 30226884, 2018).
autoimmune disease (continued). "Among the susceptibility regions for autoimmune diseases, we evaluated the polymorphisms of four genes (IL7R, CAPSL, CD226, and CLEC16A) and found the SNPs within two of these genes, IL7R and CAPSL, to be significantly associated with AITDs." (PMID 38612837, 2024). "Our findings suggest a pleiotropic role of CLEC16A and strengthen the link between PD and autoimmune diseases." (PMID 35432448, 2022). "This work was designed to better define the role of CLEC16A in NK cells, inflammation, and autoimmune disorders." (PMID 30774629, 2019). "In this study, we designed experiments to better define the role of CLEC16A in NK cells, inflammation, and autoimmune disorders." (PMID 30774629, 2019). "The loci identified included SNPs in immune response genes linked to autoimmune diseases including Crohn’s disease, ulcerative colitis, multiple sclerosis, and T1D (CD5, CCL2, IL23R, CD86, HLA, C11ORF30-LRRC32, CLEC16A)." (PMID 29454391, 2018). "Genome-wide association studies (GWASs) have also identified several non-HLA genetic variants linked to MS, including those in the interleukin-7 receptor (IL7RA), interleukin-2 receptor (IL2RA), CD58, and CLEC16A genes, indicating a shared genetic foundation with other autoimmune diseases." (PMID 40724862, 2025). "While implicated variants were largely trait-specific, 40% of target genes of these variants (2,207 of 5,488) were implicated across more than one autoimmune disorder, with 11 genes implicated across a maximum of 9 traits (e.g., TYK2, ICAM1, ICAM3, TNFIP3, CLEC16A, BACH2)." (PMID 41361473, 2025). "All in all, these data suggest that DEXI may indeed play a role in MS and other autoimmune diseases, as is the case also for its neighbouring genes, CLEC16A, CIITA and SOCS1." (PMID 39940946, 2025). "Non-HLA genes associated with sIgAD include IFIH1 and CLEC16A, both linked to autoimmune diseases like type 1 diabetes (T1D) and multiple sclerosis." (PMID 39712011, 2024). "Here, we review the emerging role of CLEC16A in autoimmune disorders and neurodegeneration." (PMID 37175930, 2023). "CLEC16A (C-Type Lectin Domain family 16A, previously known as KIAA0350) at chromosome 16p13 has been proposed as a gene region that may play a role as a susceptibility locus for autoimmune disease." (PMID 38612837, 2024). "CLEC16A (c-type lectin domain family 16, member A), which is located on human chromosome 16p13, encodes a membrane-associated endosomal protein that has been associated with T1DM, MS, primary adrenal insufficiency and other inflammatory and autoimmune diseases." (PMID 32226409, 2020). "Among them, SH2B3, CLEC16A, and TTC34 are mainly involved in immune regulation and autoimmune diseases, while other genes are involved in regulating neurological, adrenal gland, and skeletal muscle-related diseases." (PMID 38943194, 2024). "Additional immune-regulatory loci include MICA/MICB, CTLA4, PTPN22, CIITA, CLEC16A, CD274 (PD-L1), and NLRP1 (NALP1)—variants shared with other autoimmune diseases, underscoring common immune checkpoints rather than AAD-specific genes." (PMID 41465179, 2025).
Autoimmunity (14 papers, 2015 to 2025). The occurrence of an immune reaction against the organism's own cells or tissues. "C-type lectin domain family 16A (CLEC16A) is a membrane-associated endosomal protein that functions as an E3 ubiquitin ligase and is implicated in various autoimmune disorders, such as multiple sclerosis, type 1 diabetes, and systemic lupus erythematosus." (PMID 39524450, 2024). "A global knockout of CLEC16A in mice leads to abnormal mitophagy, upregulated inflammatory cytokine response, and increased risk of autoimmunity." (PMID 37175930, 2023). "Although the exact mechanism behind the suppression of autoimmunity by Clec16a deficiency is unclear, CLEC16A-dependent autophagy in TECs may regulate T cell maturation without significantly impacting the T cell repertoire." (PMID 39524450, 2024). "Interestingly, while Atg5 disruption causes autoimmunity, Clec16a knockdown mice exhibit T cell hyporeactivity and suppression of autoimmune phenotypes, even though both impair autophagy activity in TECs." (PMID 39524450, 2024). "Strong evidence has been implicated that the circCLEC16A’s parental gene CLEC16A plays important role in autoimmunity, and the variation in CLEC16A was associated with multiple immune-mediated diseases, such as type 1 diabetes, multiple sclerosis, and systemic lupus erythematosus." (PMID 34201256, 2021). "C-type lectin domain family 16, member A (CLEC16A) was first described as an autoimmunity-associated gene in a GWAS, which reported that several of its non-coding single-nucleotide polymorphism (SNP) variants were in strong linkage disequilibrium with type I diabetes in Europeans." (PMID 26121298, 2015). "Many questions still remain unanswered regarding the specific molecular mechanisms and tissue-specific contributions by which CLEC16A contributes to autoimmunity." (PMID 37175930, 2023). "Silencing of Clec16a protects against autoimmunity by inducing CD4+ T cell hyporeactivity, and CLEC16A expression is upregulated in peripheral APCs of MS patients." (PMID 33108502, 2021). "These serum Ig isotyping, cytokine, chemokine, and ISG15 results are indicative of excessive inflammatory responses in Clec16aΔUBC mice and indicate a role for CLEC16A in autoimmunity." (PMID 33795715, 2021). "We generated Clec16a inducible knockout (KO) mice to examine the functional link between CLEC16A auto-inflammation and autoimmunity." (PMID 30226884, 2018). "Investigating the convergence of SOCS and CLEC16A in the context of autoimmunity might provide a comprehensive understanding of the complex interplay between regulatory and predisposing factors, offering opportunities for innovative treatments." (PMID 38022642, 2023). "Drugs with modulatory effects on ER stress, lipophagy/autophagy/mitophagy, or inflammatory pathways could compensate for the attenuated CLEC16A activity and present formidable candidates for targeted interventions in autoimmunity and neurodegeneration." (PMID 37175930, 2023). "Two immune-regulatory genes of potential interest for autoimmunity i.e., the major histocompatibility complex (MHC) class II transactivator (CIITA) gene and the suppressor of cytokine signaling 1 (SOCS1) gene, are located close to CLEC16A." (PMID 33795715, 2021). "This work, however, does not address the complete role of CLEC16A in immune cell function, a critical component of autoimmunity." (PMID 30226884, 2018). "In addition, Clec16a knockdown in the nonobese diabetic mice protects against autoimmunity by altering the T cell selection, possibly through the inhibition of thymic epithelial cell autophagy." (PMID 35432448, 2022).
multiple sclerosis (14 papers, 2011 to 2024). A progressive autoimmune disorder affecting the central nervous system resulting in demyelination. "C-type lectin domain family 16, member A (CLEC16a) is a gene locus associated with T1D, multiple sclerosis, and adrenal dysfunction." (PMID 34691077, 2021). "The ema gene codes for Endosomal maturation defective (Ema), a homolog of the human Clec16A gene linked to multiple sclerosis." (PMID 23840387, 2013). "Both GPC6 (glypican 6) and CLEC16A (C-type lectin domain family 16, member A) are associated with multiple sclerosis." (PMID 21886828, 2011). "Clec16a has been previously identified as a susceptibility gene for type 1 diabetes, multiple sclerosis, and adrenal dysfunction, but its physiological function remains unclear." (PMID 36353377, 2022). "Another neighboring gene, CLEC16A, is a C-type lectin that has been implicated in BCR-dependent HLA-II pathway, and within the susceptibility locus for multiple sclerosis (MS)." (PMID 34352044, 2021).
type 1 diabetes (12 papers, 2015 to 2024). "For example, a type 1 diabetes susceptibility gene, Clec16a, increased rodent beta cell insulin secretion through the stimulation of a selective form of autophagy known as mitophagy, whereas humans with the susceptibility allele exhibited both reduced CLEC16A expression and increased HbA1c." (PMID 33515072, 2021). "The reason behind a concurrence between type 1 diabetes and MS in observational studies might be shared genes contributing to susceptibility to both diseases (e.g. CLEC16A and CLECL1), instead of a causal relationship." (PMID 32728946, 2021). "In 2007, we first identified the region mapping to KIAA0350 (now called C-type lectin-like domain family 16A (CLEC16A) as a novel type 1 diabetes (T1D) susceptibility locus within a 238-kb linkage disequilibrium (LD) block located on chromosome 16p13." (PMID 37175930, 2023). "Formerly, KIAA0350, now known as CLEC16A, was identified as a type 1 diabetes susceptibility locus in 2007." (PMID 37175930, 2023). "CLEC16A, identified from a GWAS of type 1 diabetes, regulates mitophagy through its interaction with NDRP1 and PARKIN." (PMID 33731350, 2021). "In our previous work in type-1 diabetes, the protective CLEC16A alleles were associated with higher levels of CLEC16A (formally known as KIAA0350)." (PMID 30774629, 2019). "More importantly, CLEC16A may be the main regulator of autoimmunity, like Type 1 diabetes, primary biliary cirrhosis, alopecia areata." (PMID 36588789, 2022). "A previous study showed that whole-body knockdown of Clec16a in non-obese diabetic (NOD) mice with type 1 diabetes reduced autophagic activity in cTECs and affected T cell selection in the thymus." (PMID 39524450, 2024).
diabetes (4 papers, 2022 to 2024). "This implies that the pathogenic human gene variants that disrupt IDPRs are novel contributors to diabetes and CLEC16A-associated diseases." (PMID 37175930, 2023). "PDX1, another gene associated with both T2D and monogenic diabetes of the young (MODY), is thought to control β-cell function by regulation of mitophagy, a key mechanism for mitochondrial turnover and quality control, through controlling of the T1D-associated gene CLEC16A." (PMID 36276935, 2022). "Mitochondrial damage in Clec16afl/fl Ins1tm1.1(cre)Thor (β cell Clec16a-KO) mice triggers a gradual decline in β cell function and diabetes onset within 4 months without dietary intervention or insulin resistance." (PMID 38935435, 2024).
asthma (3 papers, 2020 to 2023). "While some of the discovered genes were linked to asthma pathophysiology, the role of other genes such as WDR36 and CLEC16A is still uncertain and needs further investigation." (PMID 36294997, 2022). "For example, whole blood QTLs related to genes known to affect asthma pathogenesis or severity (e.g. IL18R, ZFP57, BTN3A2, NDFIP1, SMAD3, CLEC16A, and TSLP) were associated with colocalization sites for asthma and neutrophil, eosinophil, monocyte and/or lymphocyte traits." (PMID 32600345, 2020).
autoimmune thyroid disease (2 papers, 2024). Inflammatory disease of the thyroid gland due to autoimmune responses leading to lymphocytic infiltration of the gland. "This study aimed to assess the prevalence of selected single-nucleotide polymorphisms (SNPs) of Il7R, CD226, CAPSL, and CLEC16A genes in children with autoimmune thyroid diseases." (PMID 38612837, 2024).
Parkinson disease (2 papers, 2023). A progressive degenerative disorder of the central nervous system characterized by loss of dopamine producing neurons in the substantia nigra and the presence of Lewy bodies in the substantia nigra and locus coeruleus. "CLEC16A is known to play a critical role in Nrdp1-PINK-Parkin-mediated mitophagy and autophagy, and alterations in the CLEC16A expression may result in dysregulated/deficient mitophagy, increasing the likelihood of Parkinson’s disease." (PMID 37175930, 2023). "CLEC16A and CNOT1 code for autophagy- and RNA turnover-related factors, and their dysregulations are associated with Parkinson's disease and impaired neurological development, respectively." (PMID 37026480, 2023).
adenoma (1 paper, 2022). A neoplasm arising from the epithelium. "Six predicted Mir34a targets (Arhgap44, Ccnjl, Clec16a, Esyt3, Golga7b, Grap) were up-regulated in both Mir34a-deficient adenomas and tumoroids." (PMID 36147476, 2022).
Dystonia (1 paper, 2021). An abnormally increased muscular tone that causes fixed abnormal postures. "Others have noted that mechanisms underlying spinocerebellar ataxia, as well as dystonia, involves specific pathways likely crucial for Purkinje cell function, indicating CLEC16A is connected to one of these pathways." (PMID 33927318, 2021).
Hypertension (1 paper, 2026). The presence of chronic increased pressure in the systemic arterial system. "However, we identified novel genes (SBF2, ARHGAP12, EPAS1, CLEC16A, and LRPPRC) to be associated with hypertension." (PMID 41898884, 2026).
ischemia (1 paper, 2020). A hypoperfusion of the BLOOD through an organ or tissue caused by a PATHOLOGIC CONSTRICTION or obstruction of its BLOOD VESSELS, or an absence of BLOOD CIRCULATION. "We found that the LC3 II/I ratio increased markedly after ischemia, while Clec16a increased significantly after ischemia, which were both attenuated by Drp1 KO." (PMID 32312970, 2020).
ischemic stroke (1 paper, 2024). A stroke disorder caused by obstruction of blood flow to the brain, due to thrombotic (local blood clot formation) or embolic (due to a blood clot or other material traveling from another site) event. "And glucose and triglyceride metabolism are epidemiologically closely related to the occurrence of ischemic stroke, therefore, CLEC16A was linked to ischemic stroke in our study, and this study provides literature support for our genetic screen of regulatory axes." (PMID 38682035, 2024).